INS (insulin)
Diseases named in the same sentence as INS in open-access papers (continued):
Sharing a sentence is not in itself a finding about the gene and the disease.
Obesity (continued). "A four-month resistance training intervention increased FBM insulin sensitivity by 47% (p = 0.006) only in OOM, while VBM insulin sensitivity remained unchanged regardless of the maternal obesity status." (PMID 27669153, 2016). "Insulin sensitivity was decreased in nonobese PCOS women and further decreased in the presence of obesity without a clear relation with resting energy expenditure." (PMID 27672393, 2016). "Alternatively, decreased insulin sensitivity attributable to a postreceptor binding defect in the insulin signaling pathways has been identified as an intrinsic component of PCOS, independent of obesity." (PMID 27092084, 2016). "To test the hypothesis that altered plasma levels of insulin, leptin, and adiponectin are causative for EI of metabolic disorders in DIO models, we induced such hormonal changes in the absence of obesity and most of its complication in F0 male mice by administration of dexamethasone." (PMID 26662513, 2016). "A strength of this study includes similar BMI between PCOS and normal women, which helped elucidate that the relationship between AUCDCI-IPG/AUCinsulin bioactivity and insulin sensitivity is specific to PCOS and not obesity." (PMID 27721826, 2016). "Mice lacking PTP1B gene display improved insulin sensitivity with increased or prolonged tyrosine phosphorylations of IR and stay away from T2DM or obesity." (PMID 26064877, 2015). "The present study clearly showed that participants with higher CRF had significantly lower HOMA-IR and insulin values, independent of VFA levels, which is a more robust measure of obesity than the simple anthropometric measurement BMI." (PMID 25551248, 2014). "Mean fasting insulin and HOMA-IR value were statistically significantly higher in obesity with MS group when compared with the obesity without MS group (P<0.001)." (PMID 25755863, 2014). "PTP1B inhibits both insulin and leptin signaling and mice lacking PTP1B are more sensitive to both leptin and insulin and resistant to diet-induced obesity." (PMID 25147530, 2014). "Our results showed significantly higher TC, TG, LDL-C, insulin, and HOMA-IR in all obese subjects versus non-obese controls, but results vary among other international studies of apelin and obesity-related markers." (PMID 24475149, 2014). "The objective of this article is to review what is known about Meal-induced Insulin Sensitization (MIS), the consequences of the Absence of Meal-induced Insulin Sensitization (AMIS), the AMIS syndrome, and where obesity fits into the AMIS syndrome." (PMID 26237598, 2014). "In this study, obesity induced T2DM mice that received chronic administration of our novel GPR119 agonist, HD0471953, showed improved insulin sensitivity and glycemic control without severe hypoglycemia." (PMID 24386644, 2013). "Proposed reasons for the increased insulin sensitivity in PWS include relative diffuse as opposed to visceral obesity, lower GH levels, and higher ghrelin levels for the degree of obesity." (PMID 23962041, 2013). "The effect of KLF14 is reportedly not driven by obesity, quite unlike the known BMI- and fat mass mediated effect of FTO via insulin resistance." (PMID 24098730, 2013). "In obesity, JNK activity is increased in the liver, muscle, and adipose tissues, and an absence of JNK1 results in decreased adiposity and improved insulin sensitivity in obese models of mice." (PMID 23861788, 2013). "For example, GH and IGF-I were not altered in diet-induced obesity (DIO) mice and most insulin-resistant animal models investigated were male, making prolactin and the placental lactogen improbable candidates." (PMID 24133484, 2013). "Thus, LPC may be a novel insulin independent signal that regulates blood glucose levels and the reduction in circulating LPC observed in our obese mice and humans may play some role in contributing to the defects in glucose homeostasis observed in obesity and T2DM." (PMID 22848500, 2012).
Obesity (continued). "The relationship of adiposity or insulin action to circulating levels of adipose-secreted inflammatory cytokines, such as TNF-α, have not been well studied in the absence of obesity." (PMID 21589939, 2011). "We show that expression of the “obesity gene” FTO is not significantly affected by adipocyte differentiation or metabolic regulators related to glucose and insulin metabolism in our cell models of human subcutaneous adipocytes." (PMID 21687707, 2011). "Insulin sensitivity is decreased by 35%–40% in women with PCOS, independent of obesity, a decrease similar in magnitude to that seen in T2DM mellitus; however, any degree of obesity further impairs insulin action." (PMID 20396393, 2010). "Ablation of OPN does not interfere with obesity itself, but reduces ATM content, inflammation and improves insulin sensitivity of adipose tissue." (PMID 19305508, 2009). "While the attenuation of age-induced obesity in RIIβ−/− mutants does not seem to promote longevity and healthful aging by its effects on peripheral or systemic action of insulin on glucose homeostasis, it may do so by a reduction in insulin-related intracellular signaling through the IGF-1 pathway." (PMID 19536287, 2009). "The results suggest that in obesity, the physiological increase of cardiac MTP expression serves to attenuate cardiac triglyceride accumulation albeit without major effects on cardiac insulin sensitivity." (PMID 19390571, 2009). "Using FA without rotation, we found that the main factor loaded obesity (OBS) and blood pressure (BP) in African Americans; OBS and insulin (INS) in Hispanics, in Japanese, and in Whites; and OBS alone in Chinese." (PMID 16076393, 2005). "Notably, in this diet-induced obesity (DIO) model, despite observed increases in plasma insulin levels during the light photoperiod, there is no corresponding decrease in plasma lipolysis products." (PMID 39859293, 2025). "In obesity, GLUT12 is downregulated and does not respond to insulin." (PMID 38727993, 2025). "However, despite the absence of protection from diet-induced obesity, FI3KO mice exhibited markedly improved insulin sensitivity and glucose tolerance." (PMID 38816388, 2024). "In our study, we found that the proportion of maternal age ≥35, overweight and obesity were significantly higher in the women with GDM during twin pregnancies compared to those without, and this proportion further elevated in insulin-treated GDM twin pregnancies." (PMID 37946069, 2024). "The disorder of glucose and insulin metabolism has not been fully elucidated so far, and an oral glucose tolerance test (OGTT) has been the only tool used to look into the complex metabolism disorder in children and adolescents with obesity." (PMID 39767162, 2024). "In this respect, we interestingly found that insulin incubation only elicited a significant effect in healthy children’s erythrocytes, diminishing GSH conjugates toward the levels detected in negative control erythrocytes from children with obesity." (PMID 39261864, 2024). "In addition, they showed significantly elevated fasting insulin, LDL-C, free testosterone, and 2 h OGTT levels in comparison to non-PCOS adolescents affected by obesity." (PMID 38398863, 2024). "Interestingly, LECT2-deficient mice exhibited increased insulin sensitivity in skeletal muscle rather than in liver or adipose tissue, but muscle insulin sensitivity of LECT2-deficient mice was attenuated by a high-fat diet, indicating that LECT2 may be a therapeutic target for obesity-induced IR." (PMID 37180779, 2023). "In a double-blind, parallel randomised clinical trial (RCT) involving 44 subjects with overweight/obesity and prediabetes, 15 g of GOS daily, when added to a regular diet, increased Bifidobacterium by five times but did not alter peripheral insulin sensitivity, SCFAs, LPSs, or inflammatory markers." (PMID 38140329, 2023).
Obesity (continued). "In addition, a correlation was found between omentin concentrations to fasting insulin values in the non-obese group (particularly in women) and glycemia at 120 min of the OGTT in the group of men with obesity." (PMID 36830868, 2023). "By contrast, mice overexpressing ATGL in WAT moderate diet-induced obesity by promoting FAO and re-esterification within adipocytes, which result in smaller adipocyte sizes and higher insulin sensitivity without increases in serum NEFA levels or ectopic TG storage." (PMID 36626233, 2023). "It is plausible that the activity of Rac1 is regulated downstream of AMPK by mechanisms other than those in insulin signaling involving Akt2, and therefore, Rac1 activation downstream of AMPK may not be impaired by obesity." (PMID 37511290, 2023). "A reduced insulin sensitivity, attributable to a post-receptor binding defect with an alteration in the gene expression of some genes involved in insulin signaling pathways, has also been identified as an intrinsic component of PCOS, regardless of obesity presence." (PMID 37213054, 2023). "A significantly lower risk of invasive mechanical ventilation was observed in SU users than in nonusers in the female and male sex, age 50 to 80 years, no obesity, with or without smoking, CCI = 0 or ≥2, DCSI 0–≥2, OAD numbers = 0–3, with or without insulin use." (PMID 36429732, 2022). "In female Ay mice withgenetically induced obesity, unlike males, FGF21 did not affectbody weight, blood insulin levels, or POMC expression in thehypothalamus, but increased food intake and liver weight andmodified the expression of metabolic genes in the liver and inwhite adipose tissue." (PMID 35434487, 2022). "Together, the beneficial effects of WM on glucose, insulin, hepatic steatosis, and visceral adiposity indicate that preventing weight gain during this relatively short post-OVX period improves metabolic health, even without reversal of obesity." (PMID 35725493, 2022). "Among adults 18–45 years of age with obesity, within 6 years of a T2DM diagnosis, and not on insulin therapy, we will quantify the remission efficacy of a 12-week low energy diet combined with supervised exercise, followed by a 12-week phase of weight and exercise maintenance." (PMID 36130753, 2022). "The hypothesis of a direct relationship between vitamin D and insulin sensitivity (IS) and β-cell function (BCF) in a sample of non-diabetic, children with overweight/obesity and adolescents was tested." (PMID 36364954, 2022). "A high-fat diet induced increased LPS production by Gram-negative bacteria in the gut, while patients with obesity and T2DM were shown to lose weight and have increase insulin sensitivity and reduced NLRP3 and IL-1β expression after reducing their energy supply and exercising." (PMID 36232938, 2022). "Independent of obesity, SSB could serve as a contributor to a high dietary glycemic load leading to inflammation, insulin resistance, and impaired ß-cell function." (PMID 35369054, 2022). "Individuals with PWS and obesity exhibit increased insulin sensitivity and decreased fasting insulin levels relative to individuals with obesity without PWS, suggesting differences in insulin metabolism and regulation of fat patterning." (PMID 36339399, 2022). "Consistent with the reduction of obesity, treatment of KY19334, but not orlistat, specifically improved their metabolic parameters including total cholesterol, HDL-cholesterol, leptin, and resistin as well as the blood glucose level and insulin sensitivity." (PMID 36450849, 2022). "In addition, we do not imply that Treg function in coping with obesity is specifically controlled by OGT, but rather OGT is essential for most if not all Treg functions, including their regulation of insulin sensitivity and systemic metabolism." (PMID 35874700, 2022).
Obesity (continued). "To investigate these questions we compare the frequency and severity of SRBDs, as well as the frequency of certain types of SRBDs in children with simple obesity and paediatric patients with PWS, both without and during the rhGH treatment, and we correlate SRBDs with insulin resistance tests." (PMID 33670584, 2021). "Moreover, 2-h INS and 2-hBG were higher in normal-weight PCOS women than normal control indicating the metabolic aberration independent of obesity in PCOS." (PMID 34284806, 2021). "We have previously demonstrated that mice lacking endogenous OGG1 (Ogg1–/–) are prone to diet-induced obesity (DIO) and its sequelae, including insulin resistance, ectopic lipid accumulation in liver and skeletal muscle, gut dysbiosis, and chronic inflammation." (PMID 34604220, 2021). "Moreover, using a diet-induced obesity mouse model, a lack of TSP-1 was revealed to potentially reduce obesity-related inflammation and improve insulin sensitivity." (PMID 34505627, 2021). "The study findings indicated that adolescent girls with POCS and obesity had around a 50% decrease in peripheral insulin sensitivity, evidence of hepatic insulin resistance and compensatory hyperinsulinemia compared to non-PCOS girls with obesity (control group)." (PMID 34071499, 2021). "Thus, 16 weeks of periodized and non-periodized combined training similarly decreases insulin and HOMA-IR levels in adults with obesity." (PMID 34568974, 2021). "Taken together, our results suggest that substantial short-term weight loss can restore glucose homeostasis in individuals with severe obesity and NFG, IFG, and recent-onset T2DM not treated with insulin, with greater benefits accruing to those with less severe abnormalities of glucose metabolism." (PMID 31720686, 2020). "Further, TLR4 has been suggested to play a role in beta cell failure during diet-induced obesity in mice, as HFD-fed TLR4 knock out mice exhibit preserved insulin secretory function, lower inflammatory markers and no macrophage infiltration in pancreatic islets." (PMID 33178196, 2020). "Moreover, as expected healthy status was associated with better metabolic profile including lower HOMA-IR index and insulin level and higher levels of HDL, irrespective of the presence or absence of obesity." (PMID 32405361, 2020). "Please note that diabetic and obesity-promoting effects of BCAA are only possible when all three BCAA were used in combination and supplementation of single BCAA usually does not increase the insulin resistance." (PMID 32708684, 2020). "Therefore, coupled with the finding that obesity does not increase InsR expression in the ArcN, the markedly amplified increases in SNA evoked by insulin must be secondary to increases in insulin-induced cellular signaling in the ArcN." (PMID 32160920, 2020). "While certainly not obesity-resistant in these experiments, the weight gain of mice fed LFD-HFD is not correlated with elevated non-fasting plasma glucose levels, although non-fasting plasma insulin levels were elevated in mice fed LFD-HFD." (PMID 33400736, 2020). "Continued insulin aspart treatment after the intensive insulin therapy did not change TNF-α levels in T2DM patients, which might be related to obesity, lifestyle, and uncontrollable genetic factors." (PMID 31073335, 2019). "Of note, we see signs of decreased insulin sensitivity in WT LFD animals after 7 weeks, an effect probably related to the fact that, despite being low in fat, the diet is offered ad libitum and animals are not exercised, resulting in mild obesity." (PMID 30716103, 2019). "We only included horses that had obesity and EMS in this study, whilst this represents the majority of EMS cases, horses that are apparently lean but with insulin dysregulation are described 1, we cannot rule out inadvertent inclusion of such horses in our healthy control group." (PMID 30866087, 2019).
Obesity (continued). "Our study design and statistical analysis allowed the independent evaluation of the effects of obesity and of group but also their interaction, and the fact that our PCOS patients were not more insulin resistant than the control groups also eliminated this variable as a putative confounding factor." (PMID 31652917, 2019). "In the present study, we found that basal plasma norepinephrine, the principal catecholamine as an index of SNS activity, was persistently elevated and highly correlated with the plasma leptin concentration, but not plasma insulin, during high fat diet (HFD)-induced obesity in mice." (PMID 31682617, 2019). "Furthermore, Tam treatment prevented HFD-induced obesity in OVX AF2ERKI females, suggesting that ERα AF-1 can control metabolic regulation without AF-2 activation but not the accompanying insulin insensitivity commonly seen in metabolic syndrome." (PMID 30287090, 2018). "Insulin sensitivity (GDR) normalized for fat-free mass was not different between women with PCOS and obesity (p = 0.25) whereas it was significantly lower in women with T2DM (p < .0001) but highest in women with normal BMI as compared to the other three groups (p < 0.0001)." (PMID 30377436, 2018). "Two hypotheses could explain these findings, insulin sensitivity in individuals with NF1 may be mild, and it may not be sufficient to induce obesity or insulin sensitivity that is specific to non-fat tissues." (PMID 29694637, 2018). "Thus, it is insulin, and not IGF-I, that has generally been thought to play a major role in the relationship of obesity/diabetes with cancer." (PMID 29713614, 2018). "Likewise, the initiation of DM in cats is accompanied due to the obesity in correlation with high concentrations of IAPP and insulin in non-diabetic individuals." (PMID 29805204, 2018). "Moreover, improving hepatic insulin sensitivity and glucose homeostasis in the background of HFD-induced obesity did not decrease FGF21 levels in mice lacking hepatic PTP1B." (PMID 28256636, 2017). "After further HFD treatment for 4 weeks, although HFD-induced obesity was not significantly influenced by TRAF3 upregulation, mice with AdTRAF3 injection clearly exhibited increased fasting glucose and insulin levels but decreased insulin sensitivity and glucose tolerance." (PMID 26882989, 2016). "We hypothesize that the insulin-stimulated DCI-IPG mediator modulates insulin sensitivity in women with PCOS but not in normal women, and a reduction in obesity does not affect this relationship." (PMID 27721826, 2016). "In obesity it has been observed that mRNA levels of SFRP1-4, but not SFRP5, were altered; finding that SFRP1, SFRP2 and SFRP4 are adipokines and their expressions correlated with insulin sensitivity." (PMID 25922847, 2015). "Leptin-deficient ob/ob mice crossed with Erk1−/− mice are partially protected against hyperglycemia and hepatic steatosis despite developing severe obesity, suggesting that ERK signaling modulates insulin sensitivity independent of its potential direct effects on adipose tissue." (PMID 24209692, 2013). "Interestingly induction of Ser/Thr phosphorylation of IRS1 by insulin was similar in both the control and T2DM volunteers, suggesting that obesity-induced IR did not affect this aspect of insulin action." (PMID 23468892, 2013). "Furthermore, mice lacking B1R (B1−/−) exhibited improved systemic insulin sensitivity and showed resistance against high fat diet (HFD)-induced obesity." (PMID 23024762, 2012). "Additionally, compatible with our results of the downregulated BCAA metabolic pathway in obesity, adipose tissue gene expression of enzymes involved in BCAA catabolism was reduced in insulin‐resistant mice and humans with obesity compared to their nonobese counterparts in a previous study." (PMID 41077621, 2026).